ABO (ABO, alpha 1-3-N-acetylgalactosaminyltransferase and alpha 1-3-galactosyltransferase)
Diseases named in the same sentence as ABO in open-access papers (continued):
Sharing a sentence is not in itself a finding about the gene and the disease.
duodenal ulcer (9 papers, 2013 to 2023). An ulcer in the duodenal wall. "We conducted an ambispective analysis of the ABO blood group and risk of gastroduodenal ulcers (GDU) in the Japan Nurses’ Health Study (JNHS; n = 15,019)." (PMID 29093357, 2018). "SNP rs505922 on ABO was also associated with duodenal ulcer in a recessive model (OR of 1.32 with P value of 1.15×10−10)." (PMID 23704932, 2013). "We sought to investigate the association between the ABO blood group and risk of gastroduodenal ulcers (GDU) using combined analysis of both retrospective and prospective data from a large cohort study of Japanese women, the Japan Nurses’ Health Study (JNHS; n = 15,019)." (PMID 29093357, 2018). "The association between phenotypic polymorphisms of blood types, as represented by the ABO blood group, and specific diseases has been analyzed in the past by case-control studies, but few reports have shown an association of those with specific symptoms such as the presence of duodenal ulcers." (PMID 36900072, 2023). "Recently we conducted the genome wide association study for duodenal ulcer and identified disease susceptibility variations at two genetic loci corresponding to the Prostate stem cell antigen (PSCA) gene and the ABO blood group (ABO) gene." (PMID 23704932, 2013). "In our previous genome wide association study (GWAS) of duodenal ulcer using a total of 7,035 cases and 25,323 controls, we identified the significant association of genetic variations at PSCA (prostate stem cell antigen) and the ABO blood group with duodenal ulcer." (PMID 23704932, 2013).
Jaundice (9 papers, 2012 to 2025). Yellow pigmentation of the skin due to bilirubin, which in turn is the result of increased bilirubin concentration in the bloodstream. "It is well known that genetic and environmental factors influence neonatal jaundice, such as ABO incompatibility, breastfeeding and the method of delivery." (PMID 23166626, 2012). "This study revealed a changing trend in etiology contributing to neonatal jaundice in a developing nation where a significant number of cases were due to ABO incompatibility as observed in developed countries like the USA or Canada, using advanced investigations." (PMID 34513509, 2021). "The number of patients had ABO incompatibility and combined ABO and Rh incompatibilities did not significantly affect the outcome of the cases, while the number of patients had Rh incompatibility had a significant correlation with the outcome of cases of neonatal jaundice." (PMID 37545932, 2023). "Twelve-hour ETCOc levels of DAT-positive ABO-incompatible newborns were significantly higher than in DAT-negative ABO-incompatible newborns, and DAT-positive newborns had a higher rate of significant jaundice than newborns who were DAT-negative." (PMID 41007072, 2025). "The effect of rs6755571 on neonatal jaundice was not modified by maternal–fetal ABO blood group incompatibility (p value for interaction = 0.809), but it was stronger during the full term period and post term (linear interaction p value = 6.2 × 10−4)." (PMID 39214992, 2024). "Neonates whose mothers have had previously infants with jaundice were more likely to have SHB 7/22 (AOR 3.5, CI 1.10–11.5, p 0.034), of the 7 neonates with history of jaundice in previous sibling 5 had ABO/Rh discordance while the other two no reason could be identified." (PMID 36407330, 2022). "In conclusion, we found that neonates in ABO-HDN with negative DAT group developed anaemia and jaundice faster and more severely than neonates in the non-HDN group, which was approximately close to neonates in ABO-HDN with positive DAT group." (PMID 38708147, 2024).
ovarian carcinoma (9 papers, 2017 to 2025). A malignant neoplasm originating from the surface ovarian epithelium. "These genes have links to several other women’s health conditions: EBF1 mRNA have been associated with spontaneous preterm birth 20, FAM120B21 and ABO 22 have both been found to be related to ovarian cancer." (PMID 39315247, 2024). "ABO blood groups has been associated with risk of several cancers; however, the results for an association with ovarian cancer are inconsistent and little is known about the expression of histo‐blood group (ABH) antigens and ABO gene in ovarian tumor tissues." (PMID 36415180, 2023). "Ovarian cancer risk factors are relatively poorly understood, and this study lends support to ABO association with ovarian cancer risk." (PMID 36415180, 2023). "Additional research is warranted to either replicate or refute our findings, and ultimately, to determine if ABO variants and blood type are causally related to ovarian cancer development, progression, and survival." (PMID 28448592, 2017). "We conducted a retrospective cohort study of Tumor Registry confirmed ovarian cancer cases from the Vanderbilt University Medical Center with blood type from linked laboratory reports and ABO variants from linked Illumina Exome BeadChip data." (PMID 28448592, 2017). "Our previous genome-wide association study (GWAS) identified that the ABO rs633862 variant in chromosome 9q34.2 was associated with the risk of epithelial ovarian cancer (EOC) in Chinese Han women." (PMID 29109911, 2017). "Therefore, the studies to reveal the association between ABO blood group and ovarian cancer risk and the underling molecular mechanisms were needed." (PMID 36415180, 2023). "However, few studies have evaluated the association between ABO blood group and the prognosis among patients with ovarian cancer." (PMID 31777605, 2019). "Also, the association between ABO blood group and ovarian cancer was reported, but the results were opposite between Caucasians and Chinese." (PMID 29109911, 2017). "In addition, to our knowledge, there was no report on the association between genetic variations in the ABO gene and ovarian cancer survival." (PMID 29109911, 2017). "For primary ovarian cancer patients, the final model included the following features: BRCA mutation/HRD status, PARPi type, antibody-ABO, TBAs, fibrinogen concentration, and thrombin time." (PMID 40535134, 2025). "Researches of potential mechanisms for a relationship between the ABO blood group and ovarian cancer prognosis also are needed." (PMID 31777605, 2019). "As current evidence is limited, we undertook this study to evaluate blood type, ABO genetic variation, and overall survival (OS) among women with ovarian cancer." (PMID 28448592, 2017). "In addition, the mechanism for the relationship between ABO type and ovarian cancer remains almost entirely obscure, so this study is a contribution to the literature to explore this." (PMID 36415180, 2023). "The ABO gene is one frequent region of deletion in ovarian cancer." (PMID 31777605, 2019). "Therefore, we aimed to evaluate the relationship between ABO blood group and the survival of patients with ovarian carcinoma." (PMID 31777605, 2019). "Rs633862 AA genotype may function by up-regulating ABO mRNA expression, and thus contribute to clinical outcomes in Chinese ovarian cancer patients." (PMID 29109911, 2017). "Further research on ABO and ovarian cancer survival is warranted." (PMID 28448592, 2017). "Furthermore, genotype-phenotype correlation analyses suggested that rs633862 involved in regulating ABO mRNA expression, indicating its potential function on modulating ovarian cancer progression." (PMID 29109911, 2017). "Thus, further study of ABO genotypes in relation to ovarian cancer outcomes should be undertaken, for example, by OCAC." (PMID 28448592, 2017).
ovarian carcinoma (continued). "Among primary ovarian cancer patients, the variables significantly associated with PFS (P < 0.05) in the univariate analysis included BRCA mutation/HRD status, absolute value of lymphocytes (AVOL), PARPi type, antibody-ABO, total bile acids (TBAs), fibrinogen concentration, and thrombin time." (PMID 40535134, 2025). "Thus, selection of ovarian cancer cases might contribute to non-representative study populations, and differences in ABO blood type by race/ethnicity could also add to differences in findings." (PMID 28448592, 2017).
asthma (8 papers, 2009 to 2025). "Individuals with blood type A showed a higher risk of asthma, suggesting a role of ABO antigens in airway inflammation and immune regulation." (PMID 41465733, 2025). "We found associations of disease-wide susceptibility differences between the blood groups of the ABO and RhD systems, including cancer of the tongue, monocytic leukemia, cervical cancer, osteoarthrosis, asthma, and HIV- and hepatitis B infection." (PMID 36892462, 2023). "The FUT2–ABO interaction pattern looked similar to the one seen for asthma as illustrated by FUT2 × ABO stratified analysis of the risk of respiratory illnesses with detection of S. pneumoniae." (PMID 33328473, 2020). "Here, the authors identify a possible epistatic relationship between coding variants in FUT2 and ABO, especially pronounced in severe and early onset asthma." (PMID 33328473, 2020). "Because ABO typing is simple and inexpensive, it may serve as a supplementary marker for early identification of individuals with heightened susceptibility to asthma." (PMID 41465733, 2025). "We identified FUT2 and ABO variation, and epistatic effects between the two, as a genetic mechanism increasing the risk of early childhood asthma and hypothesize that this is related to the expression of AB antigens in the respiratory epithelium and involves infection with S. pneumoniae." (PMID 33328473, 2020). "The meta-analysis revealed that ABO and ATXN2 contain variants with pleiotropic effects on both COVID-19 and asthma." (PMID 35386719, 2022). "Our study demonstrates that phenotype specificity is important for the ability to detect gene–gene interactions, as evident by a strong interaction observed between the FUT2 and ABO genes only in the most severe asthma cases, as well as in the COPSAC birth cohorts with detailed clinical phenotyping." (PMID 33328473, 2020). "This is likely to be the reason for FUT2 and ABO not being detected in the previous GWAS on asthma, including much larger sample sizes." (PMID 33328473, 2020).
atherosclerosis (8 papers, 2012 to 2025). A disease characterized by the build-up of fatty material and calcium deposition in the arterial wall resulting in partial or complete occlusion of the arterial lumen. "Studies assessing the roles of ABO and RhD in subclinical atherosclerosis as potential risk markers are sparse, and the studies available have primarily included individuals already considered high-risk." (PMID 38592146, 2024). "Identification of the specific protein and lipid targets of ABO which mediate the functional effects in thrombosis, atherosclerosis and CVD is likely to provide greater opportunity for targeted therapeutic development and clinical translation." (PMID 23133757, 2012). "rs651007, close to the 5′ end of the ABO gene and significantly associated with RBC traits in our study, was the only SNP associated with decreased ferritin concentration and decreased atherosclerosis risk in a recent study of the role of iron and hepcidin in atherosclerosis." (PMID 27280446, 2016). "Our results do not confirm association of ABO rs579459, PPAP2B rs17114036, ADAMTS7 rs3825807, PIK3CG rs17398575, and EDNRA rs1878406 polymorphisms with subclinical atherosclerosis and CV disease in RA patients." (PMID 24795506, 2014).
falciparum malaria (8 papers, 2007 to 2024). "Since the study revealed a significant association of ABO blood group and severe falciparum malaria, possible role of ABO blood groups in disease outcome was explored." (PMID 22011404, 2011). "There are limited reports in literature on association of ABO blood group and susceptibility to severe falciparum malaria.." (PMID 22011404, 2011). "Severity of Plasmodium falciparum malaria is strongly correlated to the ABO blood group of the patient." (PMID 37375493, 2023). "By deciphering the structural basis of blood group preferences in rosetting, we provide a link between ABO blood grouppolymorphisms and rosette-forming adhesins, consistent with the selective role of falciparum malaria on human genetic makeup." (PMID 22807674, 2012). "Nineteen relevant publications were identified on falciparum malaria and ABO blood group." (PMID 22011404, 2011).
G6PD deficiency (8 papers, 2008 to 2025). An X-linked genetic condition caused by alterations in the gene G6PD that result in moderately to severely decreased activity levels of the enzyme glucose-6-phosphate dehydrogenase. "Pathologic jaundice can result from ABO and Rh incompatibiliy, G6PD deficiency, urinary tract infection, and hypothyroidsm." (PMID 26015822, 2015). "The impact of G6PD deficiency and ABO blood group on multiplicity of P. falciparum infection has so far not been investigated." (PMID 18215251, 2008). "In addition to G6PD deficiency, 11 out of 37 cases (29.7%) had an ABO incompatibility and one case had an Rh incompatibility." (PMID 36147809, 2022). "The most common causes of jaundice among infants with sensorineural hearing loss in our study include unknown causes, ABO and Rh incompatibility, G6PD deficiency, and sepsis." (PMID 30083525, 2018). "ABO HDN in OB setting (n=2), Rh HDN (n=2) due to anti-D + anti-C and anti-E, ABO + Rh HDN (n=1), and G6PD deficiency (n=1) were attributed to ET in HDN." (PMID 34513509, 2021).
Obesity (8 papers, 2012 to 2024). Accumulation of substantial excess body fat. "Nevertheless, some of these SNPs (rs1260326 (GCKR), rs13233571 (BCL7B), rs2847281 (PTPN2), and rs4129267 (IL6R) predicting hsCRP and rs630014 (ABO), rs651007 (ABO), and rs687289 (ABO) predicting IL-6) were associated with obesity-related traits." (PMID 28819125, 2017). "More importantly, we found that overweight and obesity could modify the effects of ABO rs651007 polymorphism on serum ALP levels." (PMID 24094242, 2013). "In addition, a significant interaction between overweight and obesity and ABO rs651007 on serum ALP was found." (PMID 24094242, 2013). "Overweight and obesity modifies the effect of ABO locus on serum ALP concentrations." (PMID 24094242, 2013). "Obesity affected 30.72% of the population, with no notable differences across ABO (p = 0.696) or Rh (p = 0.644) groups." (PMID 39803161, 2024). "The assessment of obesity, vaccination scheme completion, ABO groups, and lymphocyte and leukocyte levels was not useful in the identification of SARS-CoV-2 positive cases." (PMID 35494312, 2022).
heart failure (7 papers, 2020 to 2025). Inability of the heart to pump blood at an adequate rate to meet tissue metabolic requirements. "The trans-pQTLs associated with VWF levels were located in the ABO gene, and previous studies suggested that ABO blood groups were associated with several health and disease outcomes, e.g., hyperlipidemia, T2D, and heart failure." (PMID 36797296, 2023). "From a different perspective, the ABO gene locus has been shown to influence angiotensin-converting enzyme activity; this association suggests a potential relationship between blood type and the risk of heart failure." (PMID 35683453, 2022). "We identify and replicate associations between heart failure and one known locus in chromosome 4 near the PITX2 gene and two novel loci near the ABO (chromosome 9) and ACTN2 (chromosome 1) genes." (PMID 32111823, 2020). "The molecular interconnections between heart failure and cancer risk may be mediated by ABO and SURF1, whilst the inverse relationship between heart failure and cancer risk may be influenced by methylation and tumor immune escape pathways." (PMID 38706896, 2024). "Colocalization between GlycA and heart failure identified three genomic regions harboring the LPA, ABO, and ZNF259 genes with PP.H4 values of: 99.7, 72.2%, and 70.1%, respectively." (PMID 38892172, 2024).
Sepsis (7 papers, 2012 to 2025). Sepsis is defined as life-threatening organ dysfunction caused by a dysregulated host response to infection. "However, to the best of our knowledge, the prognostic value of ABO blood typing in sepsis has not been reported." (PMID 33076323, 2020).
bladder cancer (6 papers, 2016 to 2024). "In fact, the first reported glycosylation alterations in bladder cancer were the loss of ABO(H) blood group determinants in advanced stage carcinomas of secretor individuals, as well as changes in Lewis antigens patterns." (PMID 29207682, 2017). "Future studies are warranted to examine the role of the determinants of ABO type antigens or closely linked genetic variations in the development of bladder cancer." (PMID 28880901, 2017). "Another novel observation of the present study is the reduced risk of urinary bladder cancer for men with blood type B relative to type A. ABO blood type antigens are constitutively expressed on urothelial cells." (PMID 28880901, 2017). "Furthermore, loss of tissue ABO(H) antigens in the initial biopsy of bladder carcinomas predicts a much greater chance of subsequent invasion than in tumours with detectable ABO(H) antigens." (PMID 29207682, 2017). "Bladder cancer (BC) is the 10th most common malignancy worldwide, and some studies reported that ABO blood type or/and rhesus factor has been identified as a prognostic oncologic marker for patients with BC." (PMID 36181128, 2022). "These pathological findings suggest that the determinants of ABO blood type antigens may play a critical role in the development of urinary bladder cancer." (PMID 28880901, 2017). "In particular, abnormally low or absent expression of ABO(H)-blood group termini is commonly found in high-grade and invasive bladder cancer, while low-grade bladder cancer cells express high levels of fucosylated Lewis X antigen." (PMID 37535087, 2023).
anaemia (5 papers, 2011 to 2024). "Further, in addition to the study of anemia in cancers, research on a link between ABO antigens and malignancies has increased in recent decades." (PMID 38337488, 2024). "Nevertheless, a number of marginal protective genotype associations were also observed between specific gene mutations and anaemia (CFTR, GNAS), hyperparasitaemia (DERL3, GBP7), hyperpyrexia (GBP7, ABO) and SMA (HbS, ADCY9)." (PMID 24934404, 2014). "However, previous reports do not support an increased pernicious anaemia risk for individuals with the ABO blood group O, which indicates that the role of ABO in progression from PCA to pernicious anaemia is not straightforward." (PMID 21829393, 2011).
coagulation disorders (5 papers, 2021 to 2022). "These same variations at ABO had known associations with a spectrum of blood coagulation disorders identified in studies pre-dating COVID-19." (PMID 35482673, 2022). "At the same time, the ABO blood group, as well as pre-existing liver damage, can also affect the progress of the infection and is related to the chance of coagulopathy development." (PMID 36295093, 2022).